RN7SL551P (RNA, 7SL, cytoplasmic 551, pseudogene)
Gene: Miscellaneous RNA gene on chromosome 18 (74,227,506 to 74,227,803, forward strand). Ensembl gene ENSG00000243856.
Homologues: Orthologues: chimpanzee Metazoa_SRP (99% identical), macaque Metazoa_SRP (91% identical). Paralogues in human: RN7SL2 (84% identical), RN7SL3 (84% identical), RN7SL1 (84% identical), RN7SL126P (82% identical), RN7SL448P (81% identical), RN7SL45P (81% identical), RN7SL509P (81% identical), RN7SL230P (80% identical), RN7SL479P (80% identical), RN7SL597P (80% identical), RN7SL664P (80% identical), RN7SL769P (80% identical), and 705 more.